AMPD3 (adenosine monophosphate deaminase 3)
Description:
AMP deaminase plays a critical role in energy metabolism.
Tractability: Small molecule: it belongs to a druggable protein family. Antibody: its Gene Ontology location is reachable by antibodies, with high confidence. PROTAC: ubiquitination databases record sites on it; its protein half-life has been measured; a small molecule that binds it is known.
Target class: Enzyme; Hydrolase
Gene: Protein-coding gene on chromosome 11 (10,308,162 to 10,507,877, forward strand). Ensembl gene ENSG00000133805.
Subcellular location (Human Protein Atlas): Nuclear membrane; Nucleoli
Pathways (Reactome):
Immune System: Neutrophil degranulation
Metabolism: Purine salvage
Gene Ontology:
Molecular function: protein binding; AMP deaminase activity; deaminase activity
Biological process: AMP catabolic process; AMP metabolic process; IMP biosynthetic process; ADP catabolic process; ADP metabolic process; ATP metabolic process; erythrocyte homeostasis; GTP metabolic process; IMP salvage; nucleoside phosphate metabolic process; purine ribonucleoside monophosphate biosynthetic process
Cellular component: cytosol; extracellular region; ficolin-1-rich granule lumen; secretory granule lumen
Genetic constraint (gnomAD): Loss-of-function variants: 57 observed, 87.01 expected, observed/expected ratio (o/e) 0.66, 90% interval 0.53 to 0.82. The upper end of that interval is the gene's LOEUF score, 0.82, which puts it in group 3 of 6, group 1 being the genes least tolerant of losing a copy. Missense variants: 870 observed, 1,055.2 expected, observed/expected ratio (o/e) 0.82, 90% interval 0.78 to 0.87. Synonymous variants: 381 observed, 417.43 expected, observed/expected ratio (o/e) 0.91, 90% interval 0.84 to 0.99.
Homologues: Orthologues: chimpanzee AMPD3 (99% identical), macaque AMPD3 (99% identical), dog AMPD3 (97% identical), pig AMPD3 (97% identical), rabbit AMPD3 (96% identical), mouse Ampd3 (94% identical), rat Ampd3 (93% identical), guinea pig AMPD3 (92% identical), tropical clawed frog ampd3 (81% identical), zebrafish ampd3a (74% identical), zebrafish ampd3b (73% identical). Paralogues in human: AMPD1 (59% identical), AMPD2 (51% identical).
Diseases named in the same sentence as AMPD3 in open-access papers:
AMPD3 is named in the same sentence as 37 diseases in open-access papers, as found by Europe PMC text mining. Sharing a sentence is not in itself a finding about the gene and the disease. The quoted sentences say what the papers report.
diabetes (3 papers, 2017 to 2023). "In skeletal muscle, the expression of AMPD3 is increased by the induction of muscle atrophy, such as fasting, tumor development, renal failure, diabetes, denervation, aging, and muscle unloading." (PMID 36802195, 2023).
gastrointestinal stromal tumor (3 papers, 2022 to 2025). "There is additional evidence that AMPD3 is positively correlated with the receptor tyrosine kinase KIT in gastrointestinal stromal tumors, leading to drug resistance." (PMID 41256734, 2025). "AMPD3 catalyzes the hydrolytic deamination of AMP to form IMP, whose overexpression is associated with the malignant characteristics of gastrointestinal stromal tumors." (PMID 35574395, 2022). "AMPD3 is highly expressed in gastrointestinal stromal tumors and is upregulated in lung cancers." (PMID 35460704, 2022).
cyst (2 papers, 2021 to 2023). A sac-like closed membranous structure that may be empty or contain fluid or amorphous material. "AMP deaminase 3 (AMPD3), a key enzyme involved in AMP metabolism and AMPK activation, was found to be SE-driven in cyst development." (PMID 34901057, 2021).
ovarian carcinoma (2 papers, 2019 to 2020). A malignant neoplasm originating from the surface ovarian epithelium. "Ovarian cancer detection from cervical scrapings is feasible, using particularly promising epigenetic biomarkers such as AMPD3/NRN1/TBX15." (PMID 31775891, 2019).
Sepsis (2 papers, 2020 to 2024). Sepsis is defined as life-threatening organ dysfunction caused by a dysregulated host response to infection. "It is associated with FUT7 and AMPD3 in adult SIRS and sepsis." (PMID 32318053, 2020).
type 2 diabetes (2 papers, 2017 to 2023). "We previously demonstrated that upregulated AMP deaminase 3 (AMPD3) impairs cardiac energetics in a rat model of obese type 2 diabetes, Otsuka Long‐Evans‐Tokushima fatty (OLETF)." (PMID 36802195, 2023). "Here, we hypothesized that the cardiac BCAA levels and the activity of branched‐chain α‐keto acid dehydrogenase (BCKDH), a rate‐limiting enzyme in BCAA metabolism, are altered by type 2 diabetes (T2DM), and that upregulated AMPD3 expression is involved in the alteration." (PMID 36802195, 2023). "We recently reported that upregulated expression of AMP deaminase 3 (AMPD3), a rate‐limiting enzyme in the purine nucleotide cycle, is involved in abnormal cardiac energetics in Otsuka Long‐Evans‐Tokushima fatty (OLETF) rats, models of type 2 diabetes (T2DM)." (PMID 36802195, 2023).
alcoholism (1 paper, 2017). "While many identified genes were generally in alignment with prior knowledge, further work should be done to understand the associations between alcoholism and the five genes that went uncorroborated in the literature (BLNK, BMPER, PDLIM5, VEPH1, AMPD3)." (PMID 28361705, 2017).
atherosclerosis (1 paper, 2022). A disease characterized by the build-up of fatty material and calcium deposition in the arterial wall resulting in partial or complete occlusion of the arterial lumen. "Together, these findings in conjunction with our current study, offer biologic plausibility for AMPD3 and MICAL2 in atherosclerosis." (PMID 35020748, 2022). "Our study suggests that rare variation in genes including AMPD3, MICAL2, DPP6, and DENND2B may play a role in subclinical atherosclerosis, thereby making them promising novel candidates for the development of anti-atherosclerotic therapies." (PMID 35020748, 2022).
Atrophy (1 paper, 2017). Any weakening or degeneration, especially through lack of use. "Muscle atrophy can also alter gene expression and Ampd3 is believed to be a marker of muscle disuse and muscle denervation." (PMID 28303108, 2017).
autosomal dominant polycystic kidney disease (1 paper, 2023). Autosomal dominant form of polycystic kidney disease. "Another recent study also demonstrated that AMPD3 transcription is activated by cyclin‐dependent kinase (CDK) 7‐mediated assembly of super‐enhancer in renal tubular epithelial cells and contributes to the development of autosomal dominant polycystic kidney disease." (PMID 36802195, 2023).
cognitive decline (1 paper, 2021). "DUSP22 and RPL37 associated with rate of cognitive decline as measured by the slope of mPACC, and AMPD3 associated with the slope of CDR-SB and MCI to AD conversion status are also abundantly expressed in microglia." (PMID 34654479, 2021).
colon cancer (1 paper, 2006). "Human tryptase-ε/PRSS22, which is highly homologous to rat brain serine protease bsp2, and adenosine monophosphate deaminase 3 (AMPD3) were up-regulated in all 5 human colon cancer tissues compared to the corresponding normal mucosa." (PMID 17112382, 2006).
diabetic cardiomyopathy (1 paper, 2023). Diabetic cardiomyopathy is a disorder of the heart muscle in people with diabetes. "Together with a series of our studies on the roles of AMPD3 in dysregulated cardiac energetics and excessive production of reactive oxygen species in diabetic hearts, the present findings provide insights into mechanisms contributing to the development of diabetic cardiomyopathy." (PMID 36802195, 2023).
Glucose intolerance (1 paper, 2023). Glucose intolerance (GI) can be defined as dysglycemia that comprises both prediabetes and diabetes. "Previous publications have shown that overexpression of AMPD3 predisposes skeletal muscles to use lipids instead of glucose for energy, causing insulin resistance and glucose intolerance and insulin resistance process could be aggravated by systemic and tissue-specific alterations of lymphocyte." (PMID 37153000, 2023).
gynecological cancers (1 paper, 2019). "Whether AMPD3/NRN1/TBX15 methylations may occur in other gynecological cancers or in benign tumors remains to be determined." (PMID 31775891, 2019).
influenza (1 paper, 2025). An acute viral infection of the respiratory tract, occurring in isolated cases, in epidemics, or in pandemics; it is caused by serologically different strains of viruses (influenzaviruses) designated A, B, and C, has a 3-day incubation period, and usually lasts for 3 to 10 days. "The top-ranked genes for influenza classification included IFI27, ZFP36L1, TNC, SERTAD2, and AMPD3, several of which are known interferon-stimulated or antiviral response genes." (PMID 41020849, 2025).
prostate tumor (1 paper, 2022). "AMPD3 also showed a significantly enhanced level in prostate tumor tissue, indicating high oxidative stress and frequent transformation of nucleotides to nucleosides." (PMID 35574395, 2022).
cancer (5 papers, 2018 to 2023). A tumor composed of atypical neoplastic, often pleomorphic cells that invade other tissues. "The expression of the adenosine monophosphate deaminase 3 (Ampd3) gene downregulated 2-fold, promoting cancer cell differentiation." (PMID 37674113, 2023). "The exact role of AMPD3 in cancer is instead still unclear; however, since it controls the intracellular levels of AMP, it is reasonable to hypothesize that it might affect AMP-activated protein kinase (AMPK)." (PMID 36945054, 2023). "Although the consequences of altered expression of Ampd3 (AMP deaminase 3), a known regulator of fetal muscle and liver development, in the placenta remain to be examined, Ampd3 deficiency in cancer cells has been shown to inhibit cell proliferation and invasion." (PMID 29597262, 2018).
tumor (4 papers, 2011 to 2023). "The hazard ratios of LCLAT1 and CCDC43 are positive, indicating the anti- survival function of these genes, while the coefficients of other 5 genes are negative, including ENSG00000269386 (RAB11B-AS1), TOM1L2, AMPD3, MINK1 and WDTC1, indicating that they may be tumor suppressor genes." (PMID 28331188, 2017).
AMPD3 also shares sentences with these, for which no sentence is quoted: lung carcinoma (2 papers); pancreatic cancer (2); Alzheimer disease (1); amyotrophic lateral sclerosis (1); benign tumors (1); breast carcinoma (1); clear cell renal cell carcinoma (1); colorectal cancer (1); escherichia coli infection (1); esophageal cancer (1); hepatocellular carcinoma (1); Insulin resistance (1); non-small cell lung carcinoma (1); pneumonia (1); prostate carcinoma (1); renal failure (1); sarcopenia (1); stomach cancer (1).